TF (transferrin)
Diseases named in the same sentence as TF in open-access papers (continued):
Sharing a sentence is not in itself a finding about the gene and the disease.
brain cancer (13 papers, 2014 to 2024). A primary or metastatic malignant neoplasm affecting the brain. "Our study showed that both lower serum iron and higher transferrin levels were associated with higher risk of brain cancer." (PMID 32092884, 2020). "The creation of transferrin conjugated TPGScoated theronostic liposomes for brain cancer imaging and treatment was the goal of this study." (PMID 39091904, 2024). "Recent studies show that transferrin-decorated nanoparticles can also promote a higher cellular uptake in brain cancer cells." (PMID 37765240, 2023). "With its receptors expressed on brain capillary endothelial cells, NPs modified with transferrin (Tf) are being extensively studied for drug delivery as potential treatments for brain cancers and several neurodegenerative diseases." (PMID 34552500, 2021). "Magnetic silica PLGA nanoparticles conjugated with transferrin showed the most potent cytotoxic effect against brain cancer cells (U-87) with an IC50 of 0.13 μg mL−1." (PMID 35423427, 2021). "For instance, a drug delivery nanoparticle system involving the encapsulation of paclitaxel and conjugation of transferrin as the targeting ligand can be used to treat several types of cancer cells, including breast and brain cancer cells." (PMID 35423427, 2021). "Fluorescence microscopy results showed that rhodamine-encapsulated micelle was taken up by brain cancer cells, while competitive inhibition was observed in the presence of free HA and free transferrin." (PMID 34069106, 2021). "The bispecific aptamer had higher binding to metastatic brain cancer cells than EpCAM and transferrin aptamers alone." (PMID 29301363, 2018). "Additionally, PLGA nanoparticles loaded with methotrexate–transferrin conjugates and coated with Polysorbate 80, a water-soluble surfactant, were investigated as vehicles for brain cancer treatment." (PMID 37947732, 2023). "The OR of brain cancer was 0.69 (95% CI, 0.48, 1.00; p = 0.05), 0.75 (95% CI, 0.59, 0.97; p = 0.03), 0.41 (95% CI, 0.20, 0.88; p = 0.02) and 1.49 (95% CI, 1.04, 2.14; p = 0.03) per one SD increment of serum iron, log10 ferritin, ferritin saturation and transferrin levels." (PMID 32092884, 2020). "Transferrin (TF), for example, targets a transferrin receptor (TFR) that is overexpressed on the surface of brain capillary endothelial cells and malignant brain tumours." (PMID 38130720, 2023). "The IC50 value for P5, P5-TMZ-R, and U87 brain cancer cells after treated with free AUY922, NP-AUY922, and TF-NP-AUY922." (PMID 34069106, 2021). "Similar results were reported with transferrin-targeted PTX-NLC where the observed inhibition in U-87 brain cancer cell growth was solely attributed to the conjugation with transferrin while non-targeted PTX-loaded NLCs exhibited a surprising increase in cell viability." (PMID 32210127, 2020).
cervical cancer (13 papers, 2012 to 2025). A primary or metastatic malignant neoplasm involving the cervix. "Next, we examined the regulatory network of detected genes through ENCODE TF ChIP-Seq enrichment library and found that these genes were enriched with the previously reported TFs of Hela-S3 (cervical cancer) cell lines." (PMID 34368157, 2021). "Moreover, in vitro studies in human cervical carcinoma cell line (HeLa) showed liposomes targeted with folic acid and transferrin had higher cell association, penetration and efficacy of delivering doxorubicin compared to either of the single-ligand targeted liposomes, or non-targeted liposomes." (PMID 27447664, 2016). "Currently, there have been two main kinds of cellular antigens used as feasible targets in cervical cancer for ADCs, TF (tissue factor) and Trop2 (anti-human trophoblast cell-surface marker)." (PMID 36817443, 2023). "These glycans have been related with cervical cancer development and are present in fibroadenomas, whereas Artocarpus integrifolia lectin can recognize clusters of TF antigen." (PMID 23265237, 2012). "The anti-TF ADC Tisotumab Vedotin is the leading ADC in the field of cervical cancer." (PMID 36817443, 2023). "Tisotumab Vedotin, an anti-TF mAb (TF-011) drug conjugate has shown promising anti-tumour activity in clinical trials and is currently FDA-approved for recurrent and metastatic cervical cancer." (PMID 39105809, 2024). "As previously reported, it has been verified that after transferrin modification, Tf-CTM exhibited enhanced anti-cervical cancer treatment." (PMID 33179521, 2020). "TF-011-MMAE (HuMax-TF-ADC), an antibody drug conjugate targeting tissue factor-specific cells, exhibited excellent antitumor activity in patients with advanced solid cancers, including cervical cancer." (PMID 27447664, 2016). "Transferrin-targeted liposomes where shown to be more specific in delivery of paclitaxel to cervical cancer cell lines, compared to non-targeted liposomes." (PMID 27447664, 2016).
epilepsy (12 papers, 2017 to 2025). A brain disorder characterized by episodes of abnormally increased neuronal discharge resulting in transient episodes of sensory or motor neurological dysfunction, or psychic dysfunction. "Treatment with SVP has been linked in some research to changes in iron metabolism in epilepsy, with results including increased OS and the development of non-transferrin-bound iron." (PMID 38499882, 2024). "Nonetheless, our MR findings showed a robust causal association between high iron status (serum ferritin and transferrin saturation) and increased risk of epilepsy." (PMID 33655641, 2021). "In the human study, researchers analyzed transferrin saturation in 130 patients with epilepsy compared to 128 sex- and age-matched control subjects without epilepsy to investigate whether iron overload is a predisposing factor for epilepsy." (PMID 40808923, 2025). "The results revealed that the mean transferrin saturation of the epilepsy group was significantly higher than that of the control group." (PMID 40808923, 2025). "There is evidence that SVP therapy affects iron metabolism in epilepsy, leading to the production of non-transferrin-bound iron and an increase in OS." (PMID 38499882, 2024). "Two siblings with ID, dysmorphic features, and epilepsy were examined using mass spectrometry of serum transferrin, which revealed a CDG type 2 pattern." (PMID 34831340, 2021). "As part of a larger study examining patients with epilepsy, we obtained limited data on TF gene expression on 6 patients who were on VPA therapy at time of death (TOD) from the Human Brain Atlas of the Allen Brain Science Institute." (PMID 28271248, 2017). "The ORs of epilepsy for one standard deviation increases of the iron status biomarkers were 1.15 (95% CI, 1.02, 1.29) for serum iron, 1.37 (95% CI, 1.05, 1.80) for serum ferritin, and 1.12 (95% CI, 1.03, 1.21) for serum transferrin saturation." (PMID 33655641, 2021).
myocardial infarction (12 papers, 2012 to 2024). Gross necrosis of the myocardium, as a result of interruption of the blood supply to the area, as in coronary thrombosis. "Transferrin saturation (TS) (OR = 0.885, 95% CI = 0.797–0.982, p = 0.02) was negatively associated with the odds of Myocardial infarction (MI)." (PMID 37383700, 2023). "Cardiac microvascular endothelial TF expression has been observed in the hearts of patients with myocardial infarction, indicating that cardiac microvascular endothelial cells can express TF." (PMID 29536322, 2018). "Accordingly, TF expression has been identified in all stages of atherosclerotic lesions and significantly higher levels of circulating soluble TF have been found in patients with acute myocardial infarction and unstable angina." (PMID 27556861, 2016).
non-small cell lung carcinoma (12 papers, 2011 to 2026). A group of at least three distinct histological types of lung cancer, including non-small cell squamous cell carcinoma, adenocarcinoma, and large cell carcinoma. "In non-small-cell lung carcinomas, the increased TF expression associated with high VEGF levels and microvessel density has gained widespread acceptance." (PMID 21619686, 2011). "Polystyrene NPs were conjugated with transferrin and pre-coated with sera derived from non-small cell lung cancer (NSCLC) or diabetic and NSCLC co-morbidity patients." (PMID 36546919, 2022). "Transferrin-conjugated chitosan-PEG nanoparticles delivering paclitaxel exhibited a higher cytotoxicity towards transferrin-overexpressing human non-small cell lung cancer cells (NSCLCs) (HOP-62)." (PMID 31537986, 2019). "For example, NFκB TF has been shown to activate CD47 expression by binding to the distal enhancer elements in cells derived from breast, cervical, and non-small lung cell carcinomas." (PMID 39742254, 2024). "Transferrin (TF), a biodegradable, non-immunogenic, non-toxic, iron-transporting protein can be used as a targeting ligand to enhance the delivery of TQ into non-small cell lung carcinoma (NSCLC) cells, a lethal cancer with few treatment options." (PMID 38004545, 2023). "Herein, a multicomponent-based liposomes (Tf-PEM/L) by transferrin-modified encapsulating paclitaxel (PTX)-loaded β-elemene microemulsion (PEM) was fabricated, demonstrating significantly enhanced therapeutic efficacy against non-small cell lung cancer (NSCLC)." (PMID 41583057, 2026).
rheumatoid arthritis (12 papers, 2014 to 2026). A chronic, systemic autoimmune disorder characterized by inflammation in the synovial membranes and articular surfaces. "The pathway analysis showed that genes targeted by single miRNAs were significantly enriched in rheumatoid arthritis-Homo sapiens (human), transferrin endocytosis and recycling, oncogene-induced senescence, and G1 to S cell-cycle control." (PMID 38891641, 2024). "In a previous study, it was found that transferrin was abundant in the synovial fluid from osteoarthritic patients compared to that from patients with rheumatoid arthritis, which showed lower levels of transferrin and increased free iron." (PMID 33692196, 2021). "A study found that genetically predicted high levels of ferritin and transferrin saturation and low levels of transferrin were positively associated with gout and inversely associated with rheumatoid arthritis, while association with IBD was not supported." (PMID 36295058, 2022). "Transferrin, the negative protein of acute-phase response, also alters the glycosylation pattern in rheumatoid arthritis." (PMID 24346772, 2014).
coagulopathy (11 papers, 2011 to 2025). "When it was discovered that TF is overexpressed in cancer tissues, systemically targeting it to control tumor growth and spread – as well as cancer-associated coagulopathies – became a goal of those working at the intersection of hematology and oncology." (PMID 34395257, 2021). "Our results indicate that differences in TF expression are associated with differences in ventilator-induced coagulopathy." (PMID 22195278, 2012). "Because of extensive crosstalk between coagulation and inflammation, causing reciprocal activation and amplification, one may expect relative TF deficiency-related attenuation of ventilator-induced pulmonary coagulopathy to be associated with less pulmonary inflammation." (PMID 22195278, 2012). "Intravascular microthrombosis occurring in “DIC” has been interpreted to be a pathological coagulation disorder mediated through TF-initiated FVII activation." (PMID 30127669, 2018). "Until now “DIC” has been incorrectly ascribed to pathological coagulation disorder initiated by TF-induced coagulation." (PMID 30127669, 2018). "Having established that DMF and 4-OI potently inhibit type I IFN- and TF-mediated thrombin generation in vivo following bacterial infection, we next assessed the broader anticoagulant effects of these compounds in a model of viral-induced coagulopathy." (PMID 37316487, 2023). "Preventing TF-mediated pulmonary coagulopathy could attenuate ventilator-induced lung injury (VILI)." (PMID 22195278, 2012). "Following our findings that DMF and 4-OI block the induction and release of TF in response to LPS, thereby blocking thrombin generation in vitro, we next investigated the effects of DMF and 4-OI in vivo in a systemic model of LPS-induced inflammation and coagulopathy." (PMID 37316487, 2023). "The P‐selection and vWF were expressed in the initial phase of coagulopathy, unlike the PLAT, PAI‐1, and TF, which were upregulated in the late phase (fibrinolytic system)." (PMID 38098255, 2024).
inflammatory bowel disease (11 papers, 2015 to 2026). A spectrum of small and large bowel inflammatory diseases of unknown etiology. "Individuals with HIV-1 infection and Inflammatory Bowel Disease (IBD) or other diseases with elevated plasma LPS have increased TF expression on monocytes and TF+ microvesicles and are at increased risk for coagulopathies." (PMID 26085816, 2015).
non-alcoholic fatty liver disease (11 papers, 2013 to 2024). "It is usually diagnosed in middle-aged males presenting with moderate hyperferritinemia (< 1500 ng/ml), normal transferrin saturation, and, in half of the cases, non-alcoholic fatty liver disease (NAFLD)." (PMID 26030828, 2015).
schizophrenia (11 papers, 2007 to 2025). A major psychotic disorder characterized by abnormalities in the perception or expression of reality. "The GWAS variants represented a complex interaction profile, as exemplified by one schizophrenia-associated GWAS variant (rs1261117) that interacted with the promoter of the differentially expressed TF gene TCF4 (transcription factor 4) at all time points." (PMID 39948187, 2025). "Specifically, microarray analysis has illustrated associations between the transferrin locus and schizophrenia." (PMID 36362642, 2022). "As far as we know, this is the first study to systematically explore the influences of transferrin gene polymorphism on the antioxidant system, symptoms, and cognition, as well as the mechanism of their relationship in patients with schizophrenia." (PMID 35052629, 2022). "Polymorphisms in the transferrin gene have been found in patients with schizophrenia and were discussed to affect oligodendrocytes and myelin formation but the role in ADHD remains unclear." (PMID 40301838, 2025). "Several lines of evidence from genetic association studies implicated that brain transferrin could be involved in the pathophysiology of schizophrenia among different cohorts, including the Chinese Han population." (PMID 35052629, 2022). "Moreover, the hypothesis of the influences of transferrin rs3811655 polymorphism on the mediation model of serum Mn-SOD on schizophrenia patients’ cognition via psychotic symptoms was investigated." (PMID 35052629, 2022). "In view of the role of the iron-induced oxidative stress in the pathophysiology of schizophrenia, whether the rs3811655 polymorphism in the intron 3 of the transferrin gene might influence psychotic symptoms, cognition, and oxidative stress in schizophrenia, was investigated." (PMID 35052629, 2022). "Another study discovered that after death, patients with schizophrenia had lower levels of transferrin mRNA expression in the prefrontal cortex of brain." (PMID 36362642, 2022). "Previous findings revealed that the serum levels of transferrin were decreased in schizophrenia patients compared with normal controls." (PMID 35052629, 2022). "Previous studies have demonstrated decreased serum transferrin levels in treatment-naïve schizophrenia patients; however, some studies have reported normal serum transferrin levels in patients." (PMID 36362642, 2022). "A series of microarray analyses showed that the logarithm of the odds (LOD) scores for the transferrin gene in schizophrenia were between 2.0 and 3.0." (PMID 36362642, 2022). "Generally, the change in the expression of the transferrin gene mediated by the rs3811655 polymorphism may lead to the dysregulation of brain iron, thus resulting in abnormal dopaminergic transmission and further facilitating the psychiatric symptoms of schizophrenia." (PMID 36362642, 2022). "Genes enriched in myelin-forming oligodendrocytes were also transcriptionally downregulated in the PFC in schizophrenia subjects: myelin and lymphocyte protein (MAL), 2′,3′-cyclic nuclei 3′-phosphodiestarase, myelin-associated protein (MAG), transferrin, gelsolin, HER3 (ErbB3)." (PMID 36833173, 2023). "Microarray analysis studies have indicated a max LOD (logarithm of the odds) score of 2.0–3.0 for schizophrenia loci and transferrin loci, and it could be considered as sufficient evidence for linkage." (PMID 35052629, 2022). "However, the relationship between the polymorphism of the transferrin gene and core schizophrenia phenotypes has not been fully elucidated." (PMID 35052629, 2022). "First, although the exploratory analysis was conducted to examine the effects of genotype on hemoglobin in schizophrenia patients, we did not measure plasma transferrin levels or other iron-related proteins." (PMID 36362642, 2022).
schizophrenia (continued). "TF-genes and TF-miRNA regulatory network suggest that FOXOC1 and hsa-mir-155-5p may be identified as key regulators, while gene-disease analysis showed strong correlations with hub genes in schizophrenia and bipolar disorder." (PMID 38978778, 2024). "Moreover, the downregulation of myelin-related and oligodendrocyte genes such as proteolipid protein 1 (PLP1), transferrin (TF), oligodendrocyte transcription factor 1 (OLIG1), and upregulation of myelin basic protein (MBP) were reported in the PFC of patients with schizophrenia." (PMID 36833173, 2023). "However, the relationship between schizophrenia, its psychotic symptoms, and the transferrin (TF) gene has not been systematically explored." (PMID 35052629, 2022).
bladder cancer (10 papers, 2015 to 2024). "TF was upregulated in the bladder cancer group, which may be caused by the increased iron demand of highly proliferating cells." (PMID 38410113, 2024). "Previous research successfully identified FoxM1 as an upstream TF of HMMR in bladder cancer." (PMID 36750558, 2023). "There is a strong correlation between TF expression, VEGF production, and increased tumor angiogenesis as well as the aggressiveness of pancreas and bladder cancer." (PMID 37205313, 2023). "In contrast to our previous findings, TalaA-triggered ferroptosis of bladder cancer cells does not occur through the inhibition of SLC7A11 expression but rather through the upregulation of transferrin and heme oxygenase 1 in bladder cancer cells." (PMID 37866481, 2023).